TSPY2 (testis specific protein Y-linked 2)
Description:
May be involved in sperm differentiation and proliferation.
Synonyms: TSPYQ1
Tractability: PROTAC: ubiquitination databases record sites on it.
Gene: Protein-coding gene on chromosome Y (6,246,223 to 6,249,019, forward strand). Ensembl gene ENSG00000168757.
Subcellular location: Cytoplasm; Nucleus
Subcellular location (Human Protein Atlas): Cytosol
Gene Ontology:
Molecular function: protein binding
Biological process: nucleosome assembly
Cellular component: chromatin; cytoplasm; nucleus
Homologues: Orthologues: macaque TSPY2 (71% identical), zebrafish tspy (28% identical), Drosophila melanogaster Set (23% identical), Caenorhabditis elegans spr-2 (19% identical), Drosophila melanogaster Nap1 (15% identical), Caenorhabditis elegans nap-1 (14% identical), Drosophila melanogaster CG3708 (12% identical), Drosophila melanogaster mil (12% identical), zebrafish nap1l4a (12% identical). Paralogues in human: TSPY10 (99% identical), TSPY3 (99% identical), TSPY4 (99% identical), TSPY9 (99% identical), TSPY1 (99% identical), TSPY8 (99% identical), TSPYL1 (33% identical), TSPYL4 (31% identical), TSPYL5 (31% identical), TSPYL2 (31% identical), TSPYL6 (28% identical), SET (26% identical), and 6 more.
Diseases named in the same sentence as TSPY2 in open-access papers:
TSPY2 is named in the same sentence as 4 diseases in open-access papers, as found by Europe PMC text mining. Sharing a sentence is not in itself a finding about the gene and the disease.
TSPY2 shares sentences with these, for which no sentence is quoted: Azoospermia (1 paper); gonadoblastoma (1); melanoma (1); tumours (1).